IL10 (interleukin 10)
Diseases named in the same sentence as IL10 in open-access papers (continued):
Sharing a sentence is not in itself a finding about the gene and the disease.
colorectal cancer (continued). "Our clinical observation that patients with colorectal cancer exposed to oxaliplatin exhibited downregulation of peripheral CD45+IL-10+ cells reinforces the translational impact of our study." (PMID 38400752, 2024). "In mice with colorectal cancer cell-derived liver metastases, IL-10 upregulates PD-L1 expression in monocytes, which in turn reduces CD8+ T cell infiltration and anti-tumor immunity." (PMID 39281678, 2024). "Interrupting IL-10 signal transduction can induce the death of tumor cells in PD-1 treatment-resistant patients with colorectal cancer liver metastasis and activate the immune system’s anti-tumor response." (PMID 38903721, 2024). "The plasma levels of several cytokines (interleukin-1β /IL-1β/, IL-2, IL-4, IL-10, IL-12, IL-15, TGFβ and IFNγ) of 20 patients with colorectal cancer and 21 healthy individuals were determined by ELISA." (PMID 39456247, 2024). "A study of colorectal cancer (CRC) found that IL-10, TGF-β, and tight-junction proteins were significantly higher in the colons of mice that were given P. distasonis on a regular basis." (PMID 38441977, 2024). "BMP6 has been reported to promote IL-10 specific macrophage M2 polarization in renal cell carcinoma, which coincides with our findings in colorectal carcinoma." (PMID 38970064, 2024). "In PBMCs cocultured with colorectal cancer cells, miR-146a increased the number of Treg cells and associated suppressor cytokines, such as transforming growth factor-β (TGF-β) and IL-10." (PMID 37035756, 2023). "The increased serum level of interleukin 10 has been described as a predictor of unfavorable outcomes in patients with several cancers (colorectal cancer, renal cell carcinoma, etc.)." (PMID 36675305, 2023). "Lewis antigens can bind with DC-SIGN and induce the secretion of inflammatory cytokine secretions (e.g., IL-6 and IL-10) which can promote the establish of a tolerogenic microenvironment for colorectal cancer." (PMID 38090489, 2023). "Studies on colorectal cancer also support our finding, invasion and metastasis of colorectal cancer cells promoted by CTSK that stimulates the release of cytokines such as IL10 and IL17 through activation of the mTOR pathway." (PMID 37198626, 2023). "Binding of DC-SIGN with colorectal cancer cell glycosylated antigen promote the secretions of IL-6 and IL-10, and induce an immune tolerogenic microenvironment." (PMID 38090489, 2023). "For example, blockade of IL-10 showed anti-tumor effect in organotypic cultures of human colorectal cancer liver metastases." (PMID 36461062, 2022). "IL10RA encodes a receptor molecule for the inflammatory factor IL10 and is associated with IL10 expression and STAT3 phosphorylation in colorectal cancer." (PMID 35432443, 2022). "Some studies have shown that the level of IL-10 in patients with colorectal cancer is increased, and a positive correlation is found between the level of this cytokine and the proliferation of colon tumor cells." (PMID 35410210, 2022). "TLR2 signaling has been reported to have a protective role in inflammatory conditions and colorectal cancer, and to promote immune homeostasis by inhibiting the expression of pro-inflammatory cytokines and enhancing IL-10 production." (PMID 36439842, 2022). "In CRC, this tissue preserving and TH1-reducing activity mediated by IL-10 is one of the escape mechanisms of colorectal cancer cells leading to excessive proliferation of the tumor." (PMID 36611932, 2022). "In a colorectal cancer model, genetically modified Lactobacilli strain combinations stimulated IL-10." (PMID 36552041, 2022). "IL-10 has been found to induce TAMs (M2 polarization) in colorectal cancer promoting cancer proliferation and invasion." (PMID 35692780, 2022). "Through the secretion of IL-6, M2 macrophages mediate the expression of IL-10 by colorectal cancer cells and indirectly induce a microenvironment that suppresses T cell activity." (PMID 36611932, 2022).
colorectal cancer (continued). "STAT3 is translocated to the cell nucleus and induces IL-10 gene expression but also regulates proliferation, apoptosis, invasion, metastasis, and angiogenesis in colorectal cancer (CRC)." (PMID 35723375, 2022). "Blockade of IL-10 signalling led to restoration of T cell proliferation in the presence of M-MDSCs from both the blood and tumours of colorectal cancer patients." (PMID 34727230, 2022). "IL10 is highly expressed in colorectal cancer cells, and polarizes TAMs to the M2 phenotype, which promotes cancer cell migration and metastasis.." (PMID 34583750, 2021). "Based on suppression assays conducted in vitro, tumor-infiltrating Treg in colorectal cancer can exert immunosuppressive functions via programmed death-ligand 1 (PD-L1), IL-10 and TGF-β." (PMID 34407765, 2021). "Among other effects, the adoptive transfer of IL-10-expressing Treg cells into Rag2−/− mice inhibits colorectal carcinomas, this model reflected the suppression of host innate inflammatory response by IL-10 was pivotal in interrupting carcinogenesis." (PMID 33717103, 2021). "Using a 129/SvEv IL-10-/- mouse model of colorectal cancer, there is evidence that the nature of intestinal inflammation elicits changes in the microbiota." (PMID 33664728, 2020). "We further demonstrate that IL-10 stimulates EMT in colorectal cancer cells by activation of the STAT3- and NF-κB pathways and by promoting cancer cell proliferation." (PMID 32222879, 2020). "The failures of administration of IL-10 in IBD patients stop the step for further treating colorectal cancer patients with IL-10." (PMID 32670290, 2020). "The level of IL-10 was decreased greatly in colorectal cancer and that of Foxp3 decreased in cervical cancer after ARS treatment." (PMID 33117153, 2020). "The plasma AIMP1, KARS1, and IL-10 levels were significantly higher in the colorectal cancer patients than the healthy controls (p < 0.0001)." (PMID 32075312, 2020). "Sixty percent IL-10−/− mice develop colorectal cancer; these mice have significantly increased levels of pro-inflammatory cytokines (IFN-γ, TNF-α, IL-1β, and IL-6), indicating the chronic intestinal inflammation related with the tumor growth." (PMID 32670290, 2020). "In our clinical trial, circulating inflammatory cytokines of TNF-α, IL-10, IL-12, IL-17A, IL-17C and IL-22 remained high in colorectal cancer patients even after removal of tumor." (PMID 31340751, 2019). "LAG-3+CD4+CD25+ Treg isolated from colorectal cancer patients secrete high levels of immunosuppressive cytokines including TGFβ and IL-10, thereby maintaining the immunosuppressive milieu." (PMID 31681327, 2019). "AM0010, a recombinant human interleukin 10 (IL-10), interleukin 15 (IL-15) and interleukin 12 (IL-12) are recently used in colorectal cancer studies." (PMID 27974927, 2016). "Altogether, these results indicate that IL-10- and LPS-stimulated macrophages affect gastric and colorectal cancer cell invasion in different extents, being the IL-10-stimulated more efficient." (PMID 26043921, 2015). "In the present work, we studied LPS- and IL-10-stimulated macrophages modulation of gastric and colorectal cancer cell-related activities, such as invasion, proteolysis, motility, migration and angiogenesis and determined the associated molecular mechanisms." (PMID 26043921, 2015). "We propose that IL-10- and LPS-stimulated macrophages distinctly modulate gastric and colorectal cancer cell behaviour, as result of distinct proteolytic profiles that impact cell invasion and angiogenesis." (PMID 26043921, 2015). "In fact, within our colorectal cancer patient group we noted alterations in the IFNγ pathways in men and IL-6 in women and persistence of IL-10 under both resting and activated conditions." (PMID 22235223, 2011).
colorectal cancer (continued). "Specifically, this work centers on the SENP7-SIRT1-IL-10 axis as the conceptual core, elucidating how deSUMOylation-driven modulation of B cell senescence and IL-10 production governs immune suppression and responsiveness to immunotherapy in colorectal cancer." (PMID 41362746, 2026). "In the case of colorectal cancer, increased IL-10 levels have also been linked to a negative prognosis." (PMID 40725135, 2025). "Patients with colorectal cancer had lower methylation of the interleukin 10 signalling pathway." (PMID 38967555, 2024). "Expression of IL10 and CD274 (also known as programmed death ligand 1) was associated with tumors, such as in the clinical manifestation of laryngeal squamous cell carcinoma and colorectal cancer-derived liver metastases." (PMID 38792803, 2024). "Addressing this could ameliorate the management of colorectal cancer patients with distant metastasis by inhibiting IL-10 signaling systemically, or in an organ-specific way." (PMID 39681594, 2024). "Blocking IL-10 could also suppress the metastatic behaviors of colorectal cancer cells and promote gastrointestinal cancer cell death." (PMID 39202777, 2024). "Colorectal cancer is accompanied by an increase in tumor necrosis factor alpha (TNFα) and interleukin 10 (IL10) that exert opposite regulatory effects on barrier properties of the colon, which is characterized by morphological and functional segmental heterogeneity." (PMID 36555251, 2022). "Furthermore, Fucoidan (a long chain sulfated polysaccharide found in brown algae) increased IL-10 and valeric acid in a rat model of induced colorectal cancer." (PMID 36235651, 2022). "In colorectal cancer Ly6Clow monocyte mediated immunosuppression by IL-10 production." (PMID 34975843, 2021). "In the colorectal cancer model, mixtures of genetically modified lactobacilli strains showed the curative anticancer effect through a combination of various anti-inflammatory machinery and IL-10 stimulation." (PMID 34616233, 2021). "CoPEC promoted colorectal cancer formation in multiple intestinal neoplasia (ApcMin/+) mice, in AOM-DSS-treated mice, in IL-10-deficient (IL-10−/−) mice treated with AOM, and in Apcmin/+/IL-10−/− mice." (PMID 34063108, 2021). "Furthermore, Cer and PA attenuated expression levels of IL-10 in colorectal cancer cells co-cultured with M2 macrophages and downregulated STAT3 and NF-κB expression." (PMID 32222879, 2020). "In conclusion, IL-10 showed pro-proliferative effects on colorectal cancer cells, and this could be completely abolished by addition of Cer and PA to the co-culture." (PMID 32222879, 2020). "In this work, we investigated the influence of pro-inflammatory (LPS-stimulated) and anti-inflammatory (IL-10-stimulated) macrophages on gastric and colorectal cancer cell invasion, motility/migration, angiogenesis and proteolysis, and the associated molecular mechanisms." (PMID 26043921, 2015). "Here we generated the IL10/Nox1dKO mouse model which combines immune dysfunction (IL-10 deficiency) and abnormal epithelium (NADPH oxidase 1 (Nox1) deficiency) and spontaneously develops a UC-like phenotype with similar complications (colorectal cancer) than UC." (PMID 25014110, 2014). "The inflammatory cytokines such as IL (interleukin)-6, IL-8, IL-10, IL-12a and NOS2a (nitric oxide synthase), are positively correlated to miR-21 expression in colorectal cancer adjacent tissues, both of which are independent contributors to the poor prognosis of colorectal cancer." (PMID 24936152, 2014). "In addition, significant alterations in the IFNγ and IL-6 gender-specific pathways and IL-10 gender-common pathways were found in colorectal cancer patients." (PMID 22235223, 2011). "There is a trend to TNF-α and IFN-γ suppression with IL-10 promotion as colorectal cancer advances." (PMID 16641913, 2006).
colorectal cancer (continued). "IL-10 may also enhance weakly metastatic human colorectal carcinoma metastasis into nude mouse liver via inhibition of the production of nitric oxide (NO), reactive oxygen species (ROS), and upregulation of expression of inducible nitric oxide synthetase (iNOS) in the host liver." (PMID 37409130, 2023). "Similarly, IL-10, a feature involved in prediction of CT26 growth in our analysis, is also associated with colorectal cancer patient prognosis, but in a context dependent manner, being generally lower in patients compared to controls, but higher in patients with poor prognosis." (PMID 35226704, 2022). "It is also likely that the increased IL-10 and decreased IL-12 production in p110γ−/− macrophage might explain partly the development of colorectal carcinomas in p110γ−/− mice, because the IL-12-mediated Th1 response favors effective anti-tumor immune responses." (PMID 22053215, 2011). "Survival was negatively correlated with PD-L1, TNF-α, IL-6, and IL-10 in colorectal cancer; 4-1BB, TGF-β1, IL-8, and IL-10 in gastric cancer; and TGF-β1, IL-6, and IL-10 in pancreatic cancer." (PMID 42193466, 2026). "This study investigates the association between Fusobacterium nucleatum presence and the expression of inflammation-related genes (IL6, IL1B, IL10, IL17, TNF) in tumor and matched normal tissues from Kazakhstani patients with colorectal cancer." (PMID 41267807, 2025). "IL-6, IL-1β, IL-10, IL-17, and TNF-α were selected as key mediators of inflammation and immune regulation in colorectal cancer." (PMID 41267807, 2025). "Recent work has shown that IL-10 expression is upregulated in peritoneal metastatic lesions of both patients and mice resistant to ICB therapy in colorectal cancer." (PMID 39301023, 2024). "To further explore the effect of 23-HBA inhibition of IL-10 release from M2 macrophages on chemotherapy resistance in colorectal cancer, we conducted an analysis of STAT3 and Bcl-2, both of which serve as key mediators within the IL-10 signaling pathway." (PMID 38554148, 2024). "Matrine inhibits M2-TAM polarization by down-regulating the expression of IL-4, IL-10, and Arg-1, which can ultimately enhance TAM immune function and inhibit the growth of lung cancer and colorectal cancer." (PMID 39560523, 2024). "In colorectal cancer, M2-TAMs induced by Wnt5a-mediated CaKMII-ERK1/2-STAT3 pathway-mediated IL-10 secretion can significantly promote the growth and metastasis of intestinal cancer cells." (PMID 36160004, 2022). "Patients with stomach and colorectal cancers have been reported to have CRS evidenced by raised inflammatory markers, thrombocytopenia, elevated cytokine levels (IFN-γ/IL-2R/IL-18/IL-16/IL-10), and steroid responsiveness." (PMID 35891179, 2022). "Recently, it has also been shown that by using a long non-coding RNA (called GAS5) and inhibiting IL-10 and VEGEF-A, progression of colorectal cancer can be inhibited." (PMID 35410210, 2022). "While it is known that IL-6 promotes the EMT of cancer cells, our study showed that IL-10, secreted by M2-TAMs, induced EMT in colorectal cancer cells." (PMID 32222879, 2020). "In human colorectal cancer, infiltrating CD39+ γδ T cells, which are mainly Vδ1+ cells, produce more IL-10 than CD39- γδ T cells and CD39+ γδ T cells from the tumor-adjacent normal tissue." (PMID 33042132, 2020). "Inhibition of IL-10 secretion by M2-TAMs resulted in impairment of EMT, migratory, and proliferative capacities of colorectal cancer cells." (PMID 32222879, 2020). "IL-10 in the TME and peripheral blood portends poorer disease prognosis for ovarian cancer, more advanced stage disease in colorectal cancer, and increased tumor diameter in NSCLC." (PMID 31681327, 2019).
colorectal cancer (continued). "In NT cells treated with IL-10, the string protein interaction analysis revealed that the proteins were in KEGGS pathways related to prostate, endometrial, and colorectal cancers as well as acute myeloma leukemia." (PMID 31766635, 2019). "In line with this phenomenon, previous studies have shown that patients with bladder and colorectal cancer have decreased proportions of IFN-γ/IL-2-producing Th1 cells, while increased proportions of IL-4/IL-10-producing Th2 cells, in peripheral blood." (PMID 29849497, 2018). "Healthy colon and peripheral blood was obtained from colorectal cancer (CRC) patients undergoing colonic resection and we assessed glycoprotein B (gB, UL55) and tegument (pp65, UL83) specific IL-10/IFNγ production using fluorospot." (PMID 27926930, 2016). "Colorectal cancer patients had increased serum levels of IL-6, IL-1beta, TNF-alpha, and IL-8 but lower IL-10 concentrations." (PMID 26300773, 2015). "Similarly, in lung and colorectal cancers, elevated SPP1 expression correlates with the enrichment of M2-like TAMs, which secrete immunosuppressive cytokines such as IL-10 and TGF-β, further dampening antitumor immunity." (PMID 41391064, 2025). "CRP, procalcitonin, TNF‐α, IL‐6, IL‐10, and WBC have been used as the most common markers of inflammatory stress, and Chen used these indices to compare the efficacy of laparoscopic surgery and conventional surgery in the treatment of colorectal cancer." (PMID 38351544, 2024). "Indeed, using organotypic cell culture approaches, Sullivan and colleagues found that IL-10 blockade potentiates anti-tumor T cell responses and decreases the percentage of exhausted CD8+ T cells in human colorectal cancer liver metastases." (PMID 39281678, 2024). "The authors observed increased expression of IL-10 and IL-13 and decreased expression of IL-1β, IL-6, interferon gamma (IFN-γ), TNF-α, IL-12, and IGF-1 in peripheral blood mononuclear cells (PBMCs) derived from patients with colorectal cancer." (PMID 38957737, 2024). "Obese people with colorectal cancer had higher levels of zonulin, TMAO and IL-1β and lower levels of IL-10 than non-obese colorectal cancer patients and healthy controls." (PMID 38137918, 2023). "Moreover, it is well known that IL-10 and LPS-stimulated macrophages modulate several biochemical pathways in the TME of colorectal cancer." (PMID 35955576, 2022). "In colorectal cancer, ARS downregulated the immunosuppression by decreasing TGF-β1 and IL-10 levels, which will be beneficial for colorectal tumor patients with higher TGF-β1 and IL-10." (PMID 33117153, 2020). "Secondly, we demonstrated that IL-10 produced by M2-TAMs induced EMT in colorectal cancer cells and that Cer and PA blocked this process by inhibition of IL-10 expression and the EMT-related signaling molecules STAT3, Snail, and NF-κB in colorectal cancer cells." (PMID 32222879, 2020). "In summary, these results suggest that PA and Cer not only suppress IL-10 secretion by M2-TAMs, but also impact on IL-10 mRNA expression in colorectal cancer cells upon indirect co-culture, likely by a lack of positive-feedback signaling via IL10R." (PMID 32222879, 2020). "Such as miR-223 is upregulated in human colorectal cancer(CRC), IBD, and the IL-10 knockout mouse model of IBD, while miR-34a, miR-142–5p, miR-146a, miR-148a, and miR-223 were altered in AOM/DSS-regulated miRNAs and human IBD, and upregulated in three DSS cycles confirmed by PCR experiments." (PMID 32209121, 2020). "Therefore, we examined 6 common cytokines (IL-1β, IL-2R, IL-6, IL-8 IL-10 and TNF-α) and found colorectal cancer derived HT29 and SW480 cells expressed IL-8 and further increased after irradiation." (PMID 31706322, 2019). "Additionally, NFC shows a positive effect on increasing IL-10 and IκB-α levels in mice, indicating that NFC effectively suppresses the deterioration of inflammation in the development of AOM/DSS-induced colorectal cancer, possibly reducing the occurrence of cancer." (PMID 40292300, 2025).